PIH1D2 (PIH1 domain containing 2)
Synonyms: DNAAF15
Tractability: No criterion of Open Targets' tractability assessment is met for any kind of drug.
Gene: Protein-coding gene on chromosome 11 (112,063,218 to 112,074,274, reverse strand). Ensembl gene ENSG00000150773.
Subcellular location (Human Protein Atlas): Nucleoplasm; Basal body; Cytosol; Vesicles
Gene Ontology:
Molecular function: protein binding; small GTPase binding
Biological process: box C/D snoRNP assembly; protein stabilization; rRNA processing
Cellular component: protein folding chaperone complex; cytoplasm; R2TP complex; ribonucleoprotein complex
Genetic constraint (gnomAD): Loss-of-function variants: 25 observed, 30.03 expected, observed/expected ratio (o/e) 0.83, 90% interval 0.61 to 1.16. The upper end of that interval is the gene's LOEUF score, 1.16, which puts it in group 5 of 6, group 1 being the genes least tolerant of losing a copy. Missense variants: 278 observed, 338.41 expected, observed/expected ratio (o/e) 0.82, 90% interval 0.74 to 0.91. Synonymous variants: 108 observed, 114.91 expected, observed/expected ratio (o/e) 0.94, 90% interval 0.8 to 1.1.
Homologues: Orthologues: chimpanzee PIH1D2 (99% identical), macaque PIH1D2 (95% identical), dog PIH1D2 (83% identical), rabbit PIH1D2 (83% identical), guinea pig PIH1D2 (78% identical), mouse Pih1d2 (72% identical), pig PIH1D2 (68% identical), rat Pih1d2 (62% identical), tropical clawed frog pih1d2 (44% identical), zebrafish pih1d2 (41% identical), Drosophila melanogaster CG4022 (21% identical). Paralogues in human: DNAAF2 (22% identical), PIH1D1 (19% identical).
Diseases named in the same sentence as PIH1D2 in open-access papers:
PIH1D2 is named in the same sentence as 4 diseases in open-access papers, as found by Europe PMC text mining. Sharing a sentence is not in itself a finding about the gene and the disease. The quoted sentences say what the papers report.
carcinoma in situ (1 paper, 2018). "In the transition of squamous severe dysplasia to carcinoma in situ, the genes UBET2 PIH1D2, KIF23 showed a change in their entropy." (PMID 33265245, 2018).
esophageal carcinoma (1 paper, 2023). A primary or metastatic malignant neoplasm involving the esophagus. "Moreover, some CRGs, including PIH1D2, SLC23A2, SLC25A5, ATP7A, PDHX and COX7B, were reported to be tightly linked with the grading and immune infiltration of esophageal carcinoma." (PMID 37380924, 2023).
PIH1D2 also shares sentences with these, for which no sentence is quoted: cancer (1 paper); paraganglioma (1).